SOX2 (SRY-box transcription factor 2)
Diseases named in the same sentence as SOX2 in open-access papers (continued):
Sharing a sentence is not in itself a finding about the gene and the disease.
cancer (2,004 papers, 2008 to 2026). A tumor composed of atypical neoplastic, often pleomorphic cells that invade other tissues. "SOX2 has been implicated in the pathogenesis of various cancers, often reflecting the biology of the cell of origin." (PMID 41266112, 2026). "Studies conducted in various cancer models before clinical trials have demonstrated that cancer cells expressing SOX2 exhibit distinct characteristics associated with cancer stem cells." (PMID 40104101, 2025). "Although SOX2 itself, as a transcription factor, is not an optimal target for small-molecule therapy, this study posits the targeting of the associated E3 ligase as a promising strategy for treating cancers driven by aberrant SOX2 expression." (PMID 40034124, 2025). "From these markers, SOX2 is one of the most well-known for its association with the progression of cancers." (PMID 40918157, 2025). "By promoting oncogenic signalling and maintaining cancer stem cells, SOX2 is implicated in the development of several different cancer types, including breast, prostate, pancreatic, gastric, lung and cervical cancers." (PMID 40276932, 2025). "Its role in maintaining stem cell pluripotency and promoting cancer cell proliferation aligns with previous findings associating SOX2 with cancer aggressiveness and therapy resistance." (PMID 40674376, 2025). "In IDH-wildtype GBM, a novel SE-associated lncRNA, cancer stem cell-associated distal enhancer of SOX2 (CASCADES), has been identified as a key regulator of GSC identity through the epigenetic regulation of SOX2." (PMID 40565099, 2025). "When co-cultured with cancer-associated fibroblasts, palmitate's effect on SOX2 expression was further enhanced." (PMID 40821114, 2025). "Poor patient prognosis was associated with elevated SOX2 expression in cancers of the oral cavity, esophagus, breast, liver, rectal and prostate." (PMID 41176605, 2025). "SOX2 is also implicated in the PI3K/AKT pathway in many cancers, regulating the pathway through a feedforward regulatory manner." (PMID 40133476, 2025). "Hypoxia plays a crucial role in preserving the stem-like characteristics of cancer stem cells by promoting the expression of factors associated with stem cells, including c-Myc, Sox-2, and Oct-4, while facilitating vasculogenic mimicry (VM)." (PMID 40497987, 2025). "SOX2 expression in recurrent cancers is associated with better survival, where a SOX2 H-score above 14 is connected to reduced mortality and prolonged progression-free overall survival (prOS)." (PMID 40227667, 2025). "SOX2 has been implicated in promoting cancer stem cell function in various cancers and we have also proven it in the previous results." (PMID 39994220, 2025). "Both SC sub-types have SOX2 as a common TF; it is a core regulator of SC myelination and myelinating disorders, and is a super pioneer TF associated with cancer cell proliferation and survival." (PMID 40260118, 2025). "The dysregulation of SOX2 has been linked to the progression and metastasis of various cancers, including HCC, where it plays a role in preserving CSC properties." (PMID 40710326, 2025). "SOX2’s association with cancer stem cell behavior and PITX2’s involvement in the WNT signaling pathway underscore their roles in the pathogenesis and progression of these tumors." (PMID 40699660, 2025). "Our findings indicate benzo(a)pyrene exposure as a high-risk factor for SCLC and poor outcomes in patients, with the underlying mechanism being the activation of cancer stemness of SCLC cells via the AhR/PKA/SOX2 axis." (PMID 38791215, 2024). "This study demonstrates the clinical relevance of PIK3CA and SOX2 amplification in laryngeal tumorigenesis as early cancer risk markers beyond current histopathological grading." (PMID 38473941, 2024).
cancer (continued). "EMT changes were observed in the biomarkers related to stemness in the cancer cells and CSCs, such as sox2, oct4, and Nanog, which are associated with stem cell characteristics." (PMID 38474121, 2024). "Sox2 overexpression has been linked to oncogenic initiation, amplification, and maintenance in ovarian, lung, and pancreatic cancers." (PMID 38247819, 2024). "Our results showed that the gene ALDH3A1, associated with Ferroptosis biomarkers, and the gene SOX2, involved in cancer stemness, were both upregulated." (PMID 38206305, 2024). "Recent findings indicate CRL4-DCAF5 targets methylated proteins for ubiquitin-dependent proteolysis including SOX2 protein which is a master stem cell associated with many different types of cancers and has been proposed as an anticancer target." (PMID 38571307, 2024). "Western blotting was performed to assess the proteins that are associated with proliferation (Survivin, IL-6) and cancer stem cell function (Oct4, Sox2) in cell lysates prepared from control and etoposide treated groups." (PMID 38957610, 2024). "Aberrant Sox2 expression resulting from gene amplification, genetic alterations, or protein overexpression is frequently observed in various cancers and has been associated with poor prognosis in patients with CRC." (PMID 38473392, 2024). "LIF secreted from cancer cells and cancer‐associated fibroblasts promotes cancer stemness by driving SOX2 transcription in an autocrine/paracrine manner, respectively." (PMID 39206755, 2024). "Novel in vitro cancer stem cell-like (CSC-like) culture conditions increase the expression of stemness markers (SOX2, NANOG) and reduce DSRCT cell line susceptibility to chemotherapy while maintaining the ability of DSRCT cells to form xenografts." (PMID 38177125, 2024). "There is a link between poor prognosis and overexpression of stemness genes, with SOX2 being significantly implicated, proving the suitability of stemness genes for use in cancer management." (PMID 39684461, 2024). "The mutation landscape of SOX2 in different cancers was analyzed, and the results showed that the differential expression of SOX2 in SOX-TCF_HMG-box and SOXp was mainly related to missense mutations." (PMID 38164286, 2024). "SOX2 expression has been linked to staging, relapse, therapy resistance, and overall prognosis in several human cancers, including lung, ovarian, urothelial, breast, pancreatic, colorectal, oesophageal, nasopharyngeal and even oral squamous cell carcinoma." (PMID 39365497, 2024). "An RT-qPCR assay confirmed that the cancer stem-associated transcripts SOX2, OCT4, and NANOG were substantially upregulated by SFRP1 exposure, in both LNCaP and DU145." (PMID 36968194, 2023). "In our COSMIC analysis, we can confirm the recent findings of the Jauch lab that a few cancer variants are found at critical sites of the SOX2/17-OCT4 interaction residues (HMG boxes numbered 44, 48, 51, 55, 62, and 69)." (PMID 36672963, 2023). "Whereas the association with HERVH-CALB1 expression extended to other cancer types for some transcription factors (SOX2, SOX21), for others (TP63, FOXE1), it was specific to LUSC." (PMID 37192000, 2023). "SOX-2 dysregulation is associated with plenty of cancer types, and it has positive effects on cancer cell features such as proliferation, invasion, migration, and metastasis." (PMID 37886001, 2023). "Despite the involvement of SOX2 in the progression of multiple types of cancer, little is known about the mechanisms that cause SOX2 overexpression during tumorigenesis." (PMID 37738673, 2023). "Our results are in good agreement with a previous study that observed a marked upregulation of genes associated with cancer stem cells, such as Oct4, Sox2, Nanog, BMP2, and ALDH1, in prostate enzalutamide-resistant cells." (PMID 37958610, 2023).
cancer (continued). "Amplification and overexpression of SOX2 represent a hallmark of squamous cancers originating from diverse tissue types and play important roles in stemness maintenance of cancer stem-like cells." (PMID 36717549, 2023). "The expression of the cancer stem cell markers SOX2, OCT4, and NANOG also has been also associated to these features." (PMID 36968194, 2023). "Cancer-associated fibroblasts (CAFs) inhibit SOX2-induced dysplasia and abnormal proliferation of acinar phenotypes in the PDX model-derived TUM622 cell line, and the drug distribution interfered by new mouse stroma can also affect experimental results." (PMID 37035154, 2023). "Aside from their roles as cancer-related genes, both SOX2 and TUBB3, encoding Sox2 (Sex-determining region Y-box 2) and βIII-tubulin, respectively, play a role in the differentiation from basal cells to committed progenitor cells and, finally, adult cells." (PMID 37888115, 2023). "The design of SORE6 was built on the assumption that cancer stemness is associated with the transcriptional activity of two embryonic stem cell proteins, Sox2 and Oct4." (PMID 38203669, 2023). "miR-26a-5p overexpression suppressed the protein levels of OCT4, NANOG, and SOX2, and embryonic stem cell markers are associated with cancer stem cells, while miR-26a-5p inhibition promoted the expression of these markers." (PMID 35860691, 2022). "The net result is increased nucleus-associated YAP, leading to enhanced expression of CSLC- and cancer-promoting genes like SOX2." (PMID 35229723, 2022). "Herein, we demonstrate that cancer cell stemness, as measured by increased expression of the pluripotency-associated transcription factors Sox2, Nanog, and Oct4, appears to be required for the maintenance and potentiation of the myCAF phenotype." (PMID 36284815, 2022). "Its aberrant expression or gene amplification are commonly occurring events in cancer, where SOX2 results associated with advanced stage, poor prognosis, and drug resistance." (PMID 35944584, 2022). "SOX2 has also been shown to function downstream of ROS signals, and SOX2 is involved in hypoxia-associated modulation of cancer cell invasion, migration, and EMT." (PMID 35035654, 2022). "Overexpression of SOX2 correlates with a stem-like phenotype in cancer and has been implicated in poor survival rates of cancer patients." (PMID 36118530, 2022). "LncRNA SOX2 Overlapping Transcript (Sox2OT) is highly expressed in several cancers and has been associated with unfavorable prognosis in those cancers where it was found to promote migration and invasion through diverse mechanisms." (PMID 35455947, 2022). "Other studies reported high frequencies of CD4+ and CD8+ T cells directed against some cancer/testis antigens or SOX-2 in MGUS patients, showing significant associations with a reduced risk of progression to MM, improved disease control, and longer survival." (PMID 35563634, 2022). "The rationale behind this is that EGCG inhibits the Doxorubicin-induced pro-survival autophagy, partly through decreasing SOX2 overlapping transcript variant 7, which is a lncRNA regulator of human cancers." (PMID 35682754, 2022). "The treatment of EphrinB2-Fc on A549 cells transfected of Y594Δ caused reduced expression of Sox2 and Nanog compared to A549 cells transfected with EphB1 WT, confirming the role of EphB1 phosphorylation trans signal on cancer stem cell enrichment." (PMID 36402751, 2022). "SOX2 overlapping transcript is a lncRNA associated with cancer progression and embryonic stem cell development." (PMID 36548179, 2022). "In general, cancer stem cells usually express some of the transcription factors associated with pluripotency, such as SOX2, NANOG and OCT4)." (PMID 35954194, 2022). "The expression levels of Sox2 and Oct4 were significantly associated with each other in all tested cancer types." (PMID 33728560, 2021).
cancer (continued). "Sox2 is also closely associated with developmental disorders and multiple cancers, including lung squamous cell carcinoma, glioma, and melanoma." (PMID 34819616, 2021). "SOX2 amplification and overexpression represents a hallmark of squamous cancers with distinct distribution of chromatin accessible regions depending on cancer type." (PMID 34880227, 2021). "SOX2 balancing is important for tissue homeostasis and therefore its aberrant expression is often associated with various forms of cancers." (PMID 34768751, 2021). "Cancer stem cells are important in driving therapy resistance and transcription factors associated with pluripotency, specifically Nanog, Oct4 and Sox2, have been associated with aggressive PC." (PMID 33557087, 2021). "SOX2 expression has been suggested to act as a prognostic factor in various cancers in humans, and its increased expression has been associated with the malignancy and metastatic spread of tumors." (PMID 34072517, 2021). "Utilizing in vitro assays of cell migration, we further demonstrated that increased cancer cell progression is mechanistically linked to BCAT1-mediated regulation of SOX2 expression." (PMID 34646394, 2021). "The presence of Oct-4 and Sox-2 in MCT has consistently implicated the existence of cancer stem-like cells with active self-renewal." (PMID 34903921, 2021). "SOX2 is a reprogramming transcription factor associated with several cancer types, including CRC, and positively influences invasion/metastasis and resistance to cancer therapies." (PMID 34503224, 2021). "DMRT1 further inhibits SOX2, which is associated with a cancer stem cell state in colorectal cancer." (PMID 34108518, 2021). "Sugar modification of Sox2 was known to be involved in maintaining stemness and sometimes implicated in cancer, but the mechanism was poorly understood." (PMID 34819616, 2021). "HMGA2 directly binds to the SOX2 promotor and regulates the expression of this gene, which encodes an important cancer stem cell marker." (PMID 33668453, 2021). "SOX2 is associated with cancer cells resistance development to chemotherapy, radiotherapy, and targeted therapy in different types of human cancers." (PMID 34567804, 2021). "Cells with activated SOX2 targets displayed ES cell-like signatures with elevated subsets of ES cell-associated transcription regulators, and cancer patients with similar patterns of gene expression showed poor survival." (PMID 33767581, 2021). "Some meta-analyses also suggested the prognostic significance of SOX2 and its positive association with poor survival in human cancers." (PMID 34436030, 2021). "SOX2 is a transcriptional repressor that regulates several cellular processes associated with different types of cancer." (PMID 34503224, 2021). "The knockdown of SOX2 in cancer cells results in the loss of tumorigenicity and stemness in cancer cells." (PMID 34200614, 2021). "On the transcriptome, B4GALNT2 induced the down-regulation of the stemness-associated gene SOX2 and modulated gene expression towards an attenuation of the cancer phenotype." (PMID 32290493, 2020). "We found that almost all ciliated cells were Sox2 positive, indicating a possible association between primary cilia and the cancer stem cell population." (PMID 32811879, 2020). "SOX2 takes part in cancer stemness and its expression has been associated with CD44 and ALDH1 expression and correlated with oral squamous cell carcinoma (OSCC) metastasis." (PMID 32635524, 2020). "Consistent with the notion that developmental pathways have transforming potential when inadequately or untimely induced, dysregulated SOX2 expression was also reported as a molecular hallmark in human cancer." (PMID 32664542, 2020). "RT-qPCR was used to detect the expression of cancer stem cell-associated genes SOX2, OCT4 and Nanog." (PMID 32943985, 2020).
cancer (continued). "Evidence against SOX2 as a cancer stem cell marker comes from the report that elevated SOX2 expression in HNSCC is actually associated with a better clinical outcome in this disease, while loss of SOX2 expression conversely correlates with poor survival." (PMID 33322834, 2020). "In cancers in which SOX2 expression associates with stemness, SOX2 occurs mostly in the absence of gene amplification." (PMID 31477842, 2020). "SOX2 is a regulatory marker of cancer stem cells, and accordingly, the association between SOX2 and radiosensitivity has been widely discussed." (PMID 33182283, 2020). "Dysregulated expression of SOX2 is associated with cancer pathogenesis and several traits of cancer cells such as proliferation, EMT, CSC formation, resistance to apoptosis, and chemotherapy." (PMID 32754274, 2020). "Apart from its role in imparting stem-like characteristics to cancers, SOX2 has been implicated in developing resistance to chemotherapeutics used in common clinical set up as discussed briefly in this section." (PMID 30517668, 2020). "Stemness markers promote cancer stem cell-like formation, such as SOX2, Nanog, Oct-4, CD44, c-Myc, and KLF4, are linked to drug resistance." (PMID 33082357, 2020). "SOX2 is a core pluripotency-associated transcription factor causally related to cancer initiation, aggressiveness, and drug resistance by driving the self-renewal and seeding capacity of cancer stem cells (CSC)." (PMID 32191225, 2020). "SOX2 encodes sex-determining region Y-box 2, which is a key regulatory factor promoting cancer progression by regulating the relevant genes." (PMID 32256671, 2020). "Consistently, our study found that high expression levels of SOX2 were significantly associated with poor differentiation and lymph metastasis as well as a more advanced stage of cancer." (PMID 32144236, 2020). "By univariate analysis, Sox2 positivity of FMCs was associated with increased risk of cancer progression (HR = 1.47, 95% CI 1.00–2.15, p = 0.0388)." (PMID 33553286, 2020). "Meanwhile, the expression of cancer stem cell associated proteins, such as Sox2, Nanog, Klf4 and Myc, were also abated at different levels by AR-42 at 1 μM." (PMID 31897232, 2020). "SOX2 is involved in cancer stem cell (CSC) maintenance and is also associated with increased levels of CSC markers, including aldehyde dehydrogenase (ALDH1)." (PMID 30970654, 2019). "As CD200 overexpression increases resistance to chemoradiotherapy and leads to the acquisition of cancer stem cell-like features, sphere formation and SOX2 expression, which are associated with stem cell pluripotency in HNSCC, were evaluated." (PMID 31627350, 2019). "Pluripotency-associated transcription factors, Oct4, Sox2, and Nanog, are expressed in both embryonic stem cells and cancer stem cells." (PMID 30792401, 2019). "These AC mediated anti-cancer effects were related to the decreased expression of cancer-associated stemness marker β-catenin, SOX-2, and Nanog." (PMID 31349708, 2019). "This is indicative of an inverse relation between MTA3 and SOX2 associated with cancer occurrence and development, which was confirmed in mouse TSCC by double immunofluorescent staining." (PMID 31552166, 2019). "Sex determining region Y (SRY)-box 2 (SOX2) is a marker of cancer stem-like cells (CSCs) and is associated with the proneural molecular subtype of GBM." (PMID 31358880, 2019). "This construct should have a broader application for elucidating the functions of SOX2/OCT4-associated CSCs in multiple types of cancers." (PMID 31500347, 2019). "Sex-determining region Y (SRY)-box transcription factor 2 (SOX2) is a transcription factor whose activity is associated with cancer stem cell differentiation." (PMID 31921660, 2019). "This study was first conducted to investigate the association between CD133 or SOX2 positivity and clinical outcomes for advanced cancer patients." (PMID 30693028, 2019).